TIGIT (T cell immunoreceptor with Ig and ITIM domains)
Diseases named in the same sentence as TIGIT in open-access papers (continued):
Sharing a sentence is not in itself a finding about the gene and the disease.
tumor (continued). "Overcoming this, dual blockade of PD-1/TIGIT could successfully recapitulate anti-tumour CTL and NK cell responses in pre-clinical mouse models." (PMID 33401460, 2021). "TIGIT blockade reduces the suppressive capacity of tumor-infiltrating regulatory T cells." (PMID 34367161, 2021). "Recent studies identified the interaction of the immunomodulatory receptor TIGIT with its major ligand CD155 as a novel immune-checkpoint that may mediate tumor resistance to anti-PD-L1 immunotherapy." (PMID 33918309, 2021). "Besides, an increase of TIGIT expression with further progression of dysplasia of the tumor cells was observed (Supplement 4)." (PMID 34102454, 2021). "Thus, the clinical application of anti-TIGIT CPI immunotherapy will enhance the NK cell anti-tumour immune response and is a promising new approach towards treating HCC." (PMID 33995362, 2021). "Additionally, F. nucleatum is associated to immune evasion in cancer, avoiding NK-mediated tumor cell lysis via FAP2 interaction with the inhibitory NK-receptor TIGIT." (PMID 33841394, 2021). "In this review, we will focus on the role of TIGIT in regulating anti-tumor functions of NK cells." (PMID 34367161, 2021). "In many preclinical models, the anti-tumor activity is studied by blocking the TIGIT/PVR axis." (PMID 34631507, 2021). "Aberrant TIGIT expression results in tumor immune escape in the TME." (PMID 34433460, 2021). "Besides, preclinical studies have demonstrated that anti-TIGIT or anti-HAVCR2 can effectively control tumor evolution, suggesting a promising combination target for anti-PD-1/PD-L1 treatment." (PMID 33637086, 2021). "Currently, various clinical trials are testing the potential of TIGIT blockade in tumor patients." (PMID 34054844, 2021). "While these TIGIT positive T cells showed immune dysfunction and reduced glycometabolic activity, the treatment with TIGIT antibody could reverse the immune failure of these cells, inhibit tumor progression and induce tumor cell apoptosis." (PMID 34659197, 2021). "Inhibition of TIGIT alone or with PD-1 has shown to restore tumor-suppressive effects." (PMID 34069452, 2021). "Meanwhile, emerging evidence showed that therapies targeting PVR/TIGIT/CD96 pathways could enhance anti-tumor capacity across certain cancer types." (PMID 34150627, 2021). "Additionally, a study found that deletion of TIGIT in Tregs is effective in inhibiting tumor growth and enhancing CD8+ TIL cytotoxicity." (PMID 34433460, 2021). "TIGIT and PD-1 together can be used to mark dysfunctional T cells, and co-inhibition of TIGIT and PD-1 could trigger robust anti-tumor responses in patients with NHL." (PMID 34659197, 2021). "In multiple cancers TIGIT is expressed on tumor-infiltrating cytotoxic T cells, helper T cells, regulatory T cells and NK cells, and its main ligand CD155 is expressed on tumor-infiltrating myeloid cells and upregulated on cancer cells, which contributes to local suppression of immune-surveillance." (PMID 34367161, 2021). "Therefore, TIGIT is a pivotal inhibitory immune checkpoint that its high expression in tumoral cells and cells residing in the tumor microenvironment can remarkably attenuate anti-tumoral immune responses." (PMID 34638729, 2021). "Modified FOLFIRINOX treatment in mPDAC patients increased the proportion of CD226hiCD8+ T cells, implying that this chemotherapeutic combination may increase tumor sensitivity to anti-TIGIT treatment." (PMID 34439292, 2021). "In addition, such TIGIT overexpression was correlated with an unfavorable prognosis and tumor progression." (PMID 34659197, 2021). "Both mechanisms may contribute to the synergistic effect of dual TIGIT/PD-1 blockade on anti-tumor immunity observed in pre-clinical models, and both hypotheses are worth to be investigated." (PMID 34367161, 2021).
tumor (continued). "Indeed, TIGIT inhibition significantly delayed tumor growth in HNSCC mouse models and enhanced antitumor immune responses by activating effector CD8+ T cells and reducing immunosuppressive cells, including Tregs and MDSCs." (PMID 33804419, 2021). "In addition, anti-CD96 therapy is effective in enhancing CD8+ T activity and limiting tumor growth and is more effective when administered in combination with blockade of a number of immune checkpoints, including PD-1, PD-L1, TIGIT, and CTLA-4." (PMID 34433460, 2021). "Collectively, TIGIT blockade has convincingly been shown to enhance anti-tumor NK cell responses." (PMID 34367161, 2021). "Accordingly, TIGIT was particularly highly expressed in tumor-infiltrating T cells of MEL04." (PMID 34795004, 2021). "There is evidence that TIGIT blockade can help tumor regression." (PMID 34925314, 2021). "However, others reported that application of anti-TIGIT mAbs only reduced metastasis when combined with IL15/IL15R treatment in their tumor bearing mice models." (PMID 34276685, 2021). "TIGIT-blockade synergizes with PD-1/PDL-1 blockade to enhance anti-tumor CD8+ T-cell immunity in pre-clinical models, and is even effective in mouse tumors models that are resistant of PD-1 blockade, thus providing hope for clinical efficacy in patients with anti-PD-1 resistant tumors." (PMID 34367161, 2021). "Comparison of clinical activities of anti-human TIGIT mAbs with different Fc scaffolds could provide insight into whether FcγR binding is required for optimal anti-tumor responses of TIGIT blockades." (PMID 33670993, 2021). "It is reported that a CD47/SIRPα blockade and TIGIT/PVR blockade could elicit significant anti-tumor responses." (PMID 34068552, 2021). "Upregulation of CD226 is found in peripheral blood CD8+T cells from PDAC patients after mFOLFIRINOX chemotherapy, which is associated with an elevated responsiveness of antigen-specific CD8+T cells to treatment with anti-TIGIT or anti-PD-1 mAbs, and has also been reported in the mouse tumor models." (PMID 33670993, 2021). "Taken together, these findings indicated that the use of TIGIT antibody could restore the metabolic activity of TIGIT+ T cells and suppress tumor growth in the coculture assay." (PMID 34659197, 2021). "The response to ICIs is influenced by several factors, which can be monitored using various biomarkers, including degree of CD8 + T cell infiltration, tumor mutation burden, mismatch repair, and the expression of critical immune checkpoints (PD-1, PD-L1, CTLA-4, LAG-3, TIM3, and TIGIT)." (PMID 34367952, 2021). "However, single TIGIT-blockade has minimal effects on tumor growth in most experimental tumor models, and is also insufficient to reinvigorate functions of human tumor-infiltrating CD8+ T cells." (PMID 34367161, 2021). "In the next four paragraphs, we will discuss via which tumor-infiltrating immune cell populations TIGIT may inhibit anti-tumor immunity, and how such inhibition could be overcome." (PMID 34367161, 2021). "Furthermore, the DP EM/EMRA CD4+ and CD8+ T subsets in the tumor exhibited a significantly higher frequency of PD-1 and TIGIT-expressing T cells compared to DN T cells." (PMID 34386013, 2021). "TIGIT/PVR exerts a key role in inhibiting the anti-tumor effects of CD8 T cells and NK cells." (PMID 34367994, 2021). "CD8+ T cells in the HNSCC TME interactome, particularly with macrophages, are based on predicted CD274–PDCD1, HAVCR2–LGALS9, and TIGIT–NECTIN2 interactions that may dictate tumor rejection." (PMID 34921143, 2021). "Notably, all six expression-based markers for human TI-Tregs, TIGIT, TNFRSF9, ICOS, CCR8, CD83, and CCRL2, were ranked within the top 10%, which indicates that they are likely to play major roles in tumor-associated Treg functions." (PMID 33598101, 2021). "Antibodies dual blocking the innate checkpoint CD47 and adaptive checkpoint PD-L1 or TIGIT could achieve durable anti-tumor effects." (PMID 34068552, 2021).
tumor (continued). "In accordance with this finding, a differential level of the ligand expression, such as PVR and PD-L1, or an increase in the binding affinity of TIGIT to PVR under an acidic tumor microenvironment has been recently identified to contribute toward the sensitivity of tumor cells to TIGIT blockade." (PMID 33670993, 2021). "Further, we detected TIGIT and PD-1 expression on immune cells as well as on tumor cells." (PMID 34102454, 2021). "CTLA4, Tim3, Foxp3, GATA3, CD127, TCRab and TIGIT increased in cluster 17 of CD3+ T cell in patients with LC, of which CTLA4 expressed in tumour CD8 T cells associated with PD‐1‐mediated T‐cell dysfunction and efficacy of the checkpoint block immunotherapy in cancers." (PMID 34841705, 2021). "In a recent analysis of TILs isolated from patients with MPM, it was observed that the levels of TIGIT were significantly greater on TILs isolated from MPM compared with those isolated from tumor free lungs (TFLs), with high levels of TIGIT on ~ 60% of CD8 + T-cells." (PMID 33952230, 2021). "Moreover, the in vivo anti-tumor activity of VV-α-TIGIT was largely dependent on CD8+ T cell-mediated immunity." (PMID 33581644, 2021). "TIGIT blockade synergizes with PD-1/PD-L1 blockade to enhance anti-tumor effects of CD8+ T cells." (PMID 34367161, 2021). "We detected PD-1 and TIGIT expression on tumor cells in all morphological growth patterns, whilst in the acinar and solid growth patterns TIGIT expression on tumor cells was much higher than PD-1 expression on tumor cells (P= 0.00374 and P= 0.0012)." (PMID 34102454, 2021). "Indeed, a preclinical study showed that TIGIT blockade can prevent NK cell exhaustion and elicit potent anti-tumor immunity." (PMID 34194441, 2021). "This suggests that the TIGIT-NECTIN2 axis may likely be a tumor evasion strategy, instead of viral evasion one." (PMID 34140495, 2021). "In addition, the combination of anti-PD1 antibodies and anti-TIGIT antibodies can significantly enhance the killing effect on the tumor." (PMID 34938753, 2021). "TIGIT is an inhibitory immunoglobulin receptor that is related to tumor immune surveillance." (PMID 34943817, 2021). "In addition to inhibition of the recruitment of TILs to the tumor, F. nucleatum activates the T and natural killer (NK) cells inhibitory receptors TIGIT and CEACAM1, leading to a reduction in their ability to kill tumor cells." (PMID 34395310, 2021). "TIGIT is expressed on both T cells and NK cells and TIGIT blockade can elicit NK cell-based anti-tumor immunity, which might have specific significance for patients with AR to T cell-based ICB therapy." (PMID 34194441, 2021). "To address the involvement of these two types of cells in mediating the anti-tumor activity of VV-α-TIGIT, we depleted either CD8+ T or NK cells of mice and analyzed the impact of the depletion of these two types of cells on the therapeutic benefit by monitoring survival in H22 ascites tumor model." (PMID 33581644, 2021). "Cumulatively, these studies establish that circulating CD45RO+ Tregs from CRC patients and healthy subjects may express markers found in tumor-infiltrating Tregs, including TIGIT, OX40, and CD30." (PMID 33527196, 2021). "Furthermore, tumor infiltrating NK cells expressing PD-1, TIGIT, TIM3 are relevant for therapeutic targeting in the context of checkpoint blockade of PD-1/PD-L1 axis." (PMID 34858978, 2021). "In addition, TIGIT blockade was shown to prevent NK cell exhaustion and promote NK cell-dependent tumor immunity in several tumor-bearing mouse models." (PMID 33490104, 2020). "Moreover, TIGIT inhibition promoted tumour-specific T cell immunity and enhanced the survival of tumour-bearing mice, depending on the presence of NK cells." (PMID 32493990, 2020).
tumor (continued). "Before HBV/HCV mediated tumor initiation, TIGIT expression helps in maintaining the immune tolerance in hepatic tissue so that there is minimal immune mediated pathology, however, sustained expression of TIGIT promotes the progression of tumor by diminishing anti-tumor immunity." (PMID 32636725, 2020). "Here we significantly extend these observations and provide some mechanistic insight into how an anti-TIGIT antibody in the preclinical tumor models modulates APCs through FcγR engagement, resulting in chemokine release and activation of antigen-presenting cells (APCs)." (PMID 33117369, 2020). "The drug exposure profiles (as well as binding affinities) of anti-TIGIT: mIgG2a and anti-TIGIT:mIgG1* were found to be comparable, suggesting that the differences of anti-tumor efficacy by anti-TIGIT antibodies with different isotypes can be attributed to differences in their biological activities." (PMID 33117369, 2020). "Concurrently, CD155 could trigger intracellular signals in tumor cells upon interaction with its receptors, as formally demonstrated in DCs in which TIGIT-mediated CD155 engagement induces IL-10 secretion." (PMID 32019260, 2020). "It is relevant given that Fap2 is the bacterial outer membrane adhesin employed by F. nucleatum to bind itself to its target, in the tumor microenvironment it has been shown to impair antitumoral NK cell functions and induce lymphocytic apoptosis through TIGIT and CEACAM1 activation." (PMID 32983143, 2020). "In GBM, TIGIT has been targeted in combination with PD-1 as a strategy to overcome adaptive resistance to single checkpoint blockade while its overexpression on tumor-infiltrating immune cells correlates to their functional exhaustion." (PMID 32532329, 2020). "In summary, we have demonstrated that antagonistic anti-TIGIT antibodies with an FcγR-engaging isotype induce strong anti-tumor efficacy both when administered as a monotherapy and in combination with a PD-1 blockade in preclinical tumor models." (PMID 33117369, 2020). "Kim CG identified lower frequencies of effector/memory subtypes (CCR7- CD45RA-) in CD8+ T cells and higher frequencies of severely exhausted cells (TIGIT+) in tumor-reactive PD-1+ CD8+ T cells to predict HPD, with the area under the curve reaching 0.926 and 0.938." (PMID 32727409, 2020). "However, it is important also to consider that tumor progression facilitates the expression of the inhibitory receptors TIGIT and CD96 that compete with DNAM-1 for CD155 binding and dampen cytotoxic response." (PMID 32019260, 2020). "Similarly, the TIGIT blocking mAb overturned the exhaustion of antitumor NK cells, reactivating them and subsequently decreasing tumor growth." (PMID 33304346, 2020). "Indeed, an important mechanism of immune evasion involves decreased activating DNAM-1 and increased inhibitory TIGIT/CD96 expression on tumor infiltrating immune cells." (PMID 32069911, 2020). "It has been reported that aspirin could inhibit tumor cell growth by reducing the expression level of TIGIT, and that emodin could elicit the anti-tumor effects through downregulating the expression of PVR." (PMID 32894141, 2020). "It will be interesting to see whether any combination of anti-TIGIT (with a functional Fc) with an agent inducing immunogenic cell-death could further potentiate the efficacy of anti-tumor response in vivo." (PMID 33117369, 2020). "Intriguingly, blockade of TIGIT could further promote tumor-specific T-cell immune responses and improve memory responses to tumor rechallenge." (PMID 32140153, 2020). "In tumors, TIGIT is involved in mediating a T cell exhaustion phenotype, which is manifested by poor effector function of T cells and, consequently, decreased ability to eliminate tumor cells." (PMID 32188505, 2020). "Moreover, TIGIT+ Tregs upregulated the expression of TIM-3 in tumours, and TIM-3 and TIGIT synergized to suppress antitumour immune responses." (PMID 32680511, 2020).
tumor (continued). "Consistently, blockade of PD-1 and TIGIT results in sustained immunity in tumor models." (PMID 32903786, 2020). "While TIGIT targeting on NK cells, either alone or in combination with other ICs, leads to the restoration of anti-tumor activities, the functional consequence of TIGIT and/or CD96 blockade on ILCs remains unknown." (PMID 33255582, 2020). "Blockade of TIGIT unleashes anti-tumor CD8+ T cell by reversing mouse NK-cell dysfunction." (PMID 32403291, 2020). "Interestingly, the PD-1/TIGIT dKO mice resulted in significantly less tumor take than the PD-1 KO mice." (PMID 33117369, 2020). "Blockade of TIGIT reverses NK cell exhaustion and promotes anti-tumor immunity." (PMID 33317028, 2020). "Although it remains unclear whether increased sCD155 production is a cause of tumor development, sCD155 may modulate tumor immune responses through interaction with any, or all, of DNAM-1, TIGIT, and CD96 on T cells and NK cells." (PMID 32040157, 2020). "However, immune checkpoint genes including IDO1, HAVCR2, PDCD1LG2, CD274, CTLA4, and TIGIT were significantly up-regulated in tumor samples (fold change >1.30, FDR q ≤ 1.0e-5)." (PMID 33257699, 2020). "Indeed, several immune checkpoints, such as T cell immunoglobulin 3 (TIM3), lymphocyte activation gene 3 (LAG3), or T cell immunoglobulin and ITIM domain (TIGIT), are potential regulators contributing to the immunosuppressive tumor microenvironment in RCC." (PMID 32709062, 2020). "TIGIT+ NK cells may also be inhibited within the tumor microenvironment by MDSCs expressing the cognate ligands, thus making TIGIT a potentially prominent inhibitory receptor through various mechanisms." (PMID 32117816, 2020). "Intratumoral Tregs also express both PD-1 and TIGIT and recognize tumor-specific antigens." (PMID 33117369, 2020). "There are numerous pre-clinical studies evaluating this hypothesis and examining how blocking TIGIT affects an anti-tumor immune response." (PMID 33304346, 2020). "Specifically, tumor cells expressed PD-L1 (encoded by CD274) and PVR transcripts, which could transmit inhibitory signals to PD-1 (encoded by PDCD1 gene) and TIGIT on T cells, respectively." (PMID 32460812, 2020). "Similar studies in human peripheral blood NK cells showed that TIGIT blockade enhanced their anti-tumor activity against soft-tissue sarcoma and ovarian carcinoma tumor targets in vitro, and significantly, reduced tumor burden of mice with ovarian carcinoma xenografts." (PMID 33371456, 2020). "Blockade of TIGIT with Abs could effectively reverse NK cell exhaustion and enhance NK-cell-dependent antitumor immune responses in several tumor-bearing mouse models." (PMID 32140153, 2020). "Early-phase trials of anti-TIM3 and anti-TIGIT antibodies are also ongoing in multiple tumor types." (PMID 32709062, 2020). "The data demonstrating significantly enhanced anti-tumor efficacy with anti-TIGIT: mIgG2a antibody as compared to anti-TIGIT:mIgG1* antibody suggests that the interaction of the Fc portion of the anti-TIGIT antibody with FcγRs plays a critical role in its ability to achieve anti-tumor activity." (PMID 33117369, 2020). "Blocking TIGIT by genetic targeting or blocking antibodies could effectively inhibit tumor growth in mice and significantly prolong the survival of tumor-bearing mice." (PMID 33344447, 2020). "We followed tumor growth and could demonstrate that TIGIT-28/F4 T-cells mediated a significant delay in tumor growth compared to the control group that was treated with control-F4 transduced T-cells (n = 10, p = 4.2e-5, measured by ANOVA)." (PMID 31500665, 2019). "This suggests that TIGIT-28 transduced cells may function better in a hostile tumor microenvironment compared to unmanipulated cells." (PMID 31500665, 2019). "Similarly to other immune checkpoint ligands, TIGIT ligands are often overexpressed in cancer cells while TIGIT is significantly upregulated in chronically stimulated or exhausted tumor-infiltrating T cells." (PMID 31500665, 2019).